STMN1 (stathmin 1)
Description:
Involved in the regulation of the microtubule (MT) filament system by destabilizing microtubules. Prevents assembly and promotes disassembly of microtubules. Phosphorylation at Ser-16 may be required for axon formation during neurogenesis. Involved in the control of the learned and innate fear (By similarity).
Synonyms: Op18; pp19; C1orf215; LAP18; SMN; PR22; PP17; Lag; FLJ32206
Tractability: PROTAC: ubiquitination databases record sites on it; its protein half-life has been measured.
Target class: Other cytosolic protein
Gene: Protein-coding gene on chromosome 1 (25,884,181 to 25,907,237, reverse strand). Ensembl gene ENSG00000117632.
Subcellular location: Cytoplasm, cytoskeleton
Subcellular location (Human Protein Atlas): Cytosol
Pathways (Reactome):
Signal Transduction: Nuclear signaling by ERBB4
Gene Ontology:
Molecular function: protein binding; tubulin binding
Biological process: hepatocyte growth factor receptor signaling pathway; microtubule depolymerization; mitotic cytokinesis; mitotic spindle organization; regulation of microtubule polymerization or depolymerization; response to virus; intracellular signal transduction; neuron projection development; signal transduction
Cellular component: extracellular exosome; cytoplasm; cytosol; neuron projection; cytoskeleton; membrane
Genetic constraint (gnomAD): Loss-of-function variants: 3 observed, 19.22 expected, observed/expected ratio (o/e) 0.16, 90% interval 0.07 to 0.4. The upper end of that interval is the gene's LOEUF score, 0.4, which puts it in group 1 of 6, group 1 being the genes least tolerant of losing a copy. Missense variants: 99 observed, 185.53 expected, observed/expected ratio (o/e) 0.53, 90% interval 0.45 to 0.63. Synonymous variants: 59 observed, 62.24 expected, observed/expected ratio (o/e) 0.95, 90% interval 0.77 to 1.18.
Homologues: Orthologues: guinea pig STMN1 (99% identical), mouse Stmn1 (99% identical), pig STMN1 (97% identical), rat LOC102546674 (92% identical), chimpanzee STMN1 (89% identical), macaque STMN1 (86% identical), tropical clawed frog stmn1 (77% identical), zebrafish stmn1a (76% identical), zebrafish stmn1b (75% identical), dog STMN1 (66% identical), Drosophila melanogaster stai (39% identical). Paralogues in human: STMN2 (69% identical), STMN4 (64% identical), STMN3 (63% identical), STMND1 (26% identical).
Diseases named in the same sentence as STMN1 in open-access papers:
STMN1 is named in the same sentence as 153 diseases in open-access papers, as found by Europe PMC text mining. Sharing a sentence is not in itself a finding about the gene and the disease. The quoted sentences say what the papers report.
breast carcinoma (51 papers, 2000 to 2026). "High STMN1 levels are linked to aggressive phenotypes in breast cancer 54, while its regulation by tumor suppressor miRNAs, such as miRNA-223 and miR-34a 55, 56, underscores its role in tumor progression." (PMID 40225568, 2025). "STMN1 has been associated with breast cancer due to its influence on cell proliferation, differentiation, and motility." (PMID 39057719, 2024). "Specifically, phosphorylation at serine residues 25 (ser25) and 38 (ser38) of STMN1 was shown to be increased in cells with higher metastatic potential and was also associated with increased morbidity and mortality in breast cancer patients." (PMID 39057719, 2024). "STMN1 is a microtubule destabilizing protein whose expression is associated with breast cancer proliferation." (PMID 36009568, 2022). "In conclusion, we showed that STMN1 expression and phosphorylation at multiple serine residues plus clinicopathological characteristics have significant predictive value for breast cancer-associated disease events including recurrence." (PMID 26087399, 2015). "STMN1 phosphorylation on S16 or S63 was strongly associated with improved disease-free survival, while phosphorylation on S25 or S38 was associated with poorer disease-free survival in patients with luminal subtype breast cancer." (PMID 40723207, 2025). "STMN1 expression was associated with aggressive phenotypes in breast cancer." (PMID 33921319, 2021). "Published studies have consistently reported that elevated STMN1 expression is associated with poorer survival in various cancers, including head and neck squamous cell carcinoma, gallbladder carcinoma, esophageal squamous cell carcinoma, breast cancer, and endometrial carcinoma." (PMID 38114977, 2023). "Moreover, elevated STMN1 is linked to high histological grade and low ER, PR expression status, and the aggressive phenotypes accompanied with cancer stem cell marker expression of breast cancer." (PMID 36009568, 2022). "STMN1 is overexpressed in many cancers, including prostate and breast cancer, and studies on STMN1 typically analyze total STMN1 expression by gene expression profiling and immunohistochemistry of clinical cancer samples or cancer cell lines." (PMID 40723207, 2025). "STMN1 is highly expressed in different types of cancers such as colorectal, gallbladder, breast cancer, hepatocellular carcinoma, sarcoma, lung and prostate adenocarcinomas." (PMID 38893174, 2024). "STMN1 expression is correlated with the clinical outcome of patients with breast cancer, glioma and hepatocellular carcinoma." (PMID 38893174, 2024). "Another study found that STMN1 can be used as a prognostic indicator, based on elevated STMN1 leading to a worse prognosis in breast cancer patients." (PMID 39057719, 2024). "At 48 h, breast cancer regulation by Stathmin 1 (microtubule regulation) and factors promoting cardiogenesis in vertebrates (Wnt/Bmp axis) occurred in addition to other immune and neural pathways." (PMID 37762531, 2023). "The IPA confirmed the enrichment of pathways involved in TME and ECM, which are reported to be essential non-cellular components of TME, GPCR, and PI3K activation (as indicated by breast cancer regulation by Stathmin 1 pathway in IPA) in ERFEhigh cancers." (PMID 36675239, 2023). "Other authors demonstrated that miR-101 is hypo-expressed in different breast cancer subtypes and stimulates cellular proliferation and invasiveness by targeting Stathmin1 (Stmn1)." (PMID 34442460, 2021). "The proportion of up-regulated transcripts in breast cancer regulation by the stathmin-1 pathway was similar at Baseline to after supplementation with tCSO, but approximately 3-fold greater after FO supplementation." (PMID 34578993, 2021).
breast carcinoma (continued). "LongGF also detected more potential novel gene fusions (ACTB:H3F3B, SLC25A24:NBPF6, STMN1:ACTG1), and these genes were reported to be associated with breast cancer." (PMID 33372596, 2020). "Conversely, overexpression of STMN1, which is a direct functional target of miR-770, promoted breast cancer cell DOX resistance and metastasis." (PMID 29323124, 2018). "Taken together, these findings indicated that STMN1 mRNA is a direct, down-stream target of miR-770 in breast cancer cells." (PMID 29323124, 2018). "Consistent with our results, STMN1 has been reported to be related to TX sensitivity in ovarian cancer and breast cancer as well, while targeting STMN1 by RNA interference can sensitize STMN1-overexpressing breast cancer cells to TX." (PMID 25897432, 2015). "STMN1 upregulation was also reported in the highly proliferative breast cancers and in ovarian cancers." (PMID 25897432, 2015). "Our report is the first in our knowledge to identify the importance of the combination of STMN1 and its multiple phosphorylations in breast cancer." (PMID 26087399, 2015). "In this study of breast cancer, STMN1 expression and the phosphorylation status of its multiple serine residues were better correlated with DFS than standard clinicopathological features." (PMID 26087399, 2015). "We developed a novel prognostic model based on STMN1 and its multiple phospho-sites, in addition to several clinicopathological factors, to improve the prognosis of recurrence after surgery for breast cancer patients." (PMID 26087399, 2015). "A reverse correlation was also found between the level of miR-101 and Stmn1 in human breast cancer tissues." (PMID 23071542, 2012). "More importantly, in vivo analysis found that Stmn1 mRNA and protein level in different subtypes of human breast cancer tissues, contrary to the down-regulation of miR-101, were significantly elevated." (PMID 23071542, 2012). "The results from the analysis of the trend of Stmn1 expression in four different subtypes of breast cancer tissues were consistent with that in all breast cancer tissues." (PMID 23071542, 2012). "In general, the expression of Stmn1 was significantly higher in all human breast cancer tissues than that in adjacent normal breast tissues (P<0.01; Figure 9B1)." (PMID 23071542, 2012). "The expression of Stmn1 was significantly increased as miR-101 decreased in human breast cancer tissues." (PMID 23071542, 2012). "(iii) In this study, we found that the level of Stmn1 expression was up-regulated, consistent with previous reports, and miR-101 was down-regulated in human breast cancer tissues." (PMID 23071542, 2012). "The overall expression of Stmn1 was significantly enhanced in human breast cancer tissues of triple negative (P<0.01), ER/PR+, HER2+ (P<0.01), ER/PR+, HER2− (P<0.05) and ER/PR−, HER2+ (P<0.05) (Figure 9B2–5)." (PMID 23071542, 2012). "The distribution of STMN1 in breast cancer tissues and adjacent normal breast tissues was determined by immunohistochemistry." (PMID 23071542, 2012). "The results of western blot showed that the protein level of Stmn1 was significantly increased in all breast cancer tissues and four subtypes, respectively, compared with adjacent normal breast tissues (P<0.05)." (PMID 23071542, 2012). "Thus, a positive correlation between STMN1, MET, and HGF expression and metastasis, responsiveness to taxane, and overall survival in prostate and breast cancer patients is based on total STMN1 expression within these tumors." (PMID 40723207, 2025). "Several existing studies have suggested that resistance to PTX analogues may arise from altered interactions among microtubule proteins, including STMN1 in breast cancer." (PMID 41361792, 2025).
breast carcinoma (continued). "While the function and targeting of STMN1 have been characterised in a variety of cancers ranging from lung and breast cancers to leukaemia, the functional role of STMN1 in prostate cancer metastasis remains unknown." (PMID 39402324, 2024). "Shared pathways between LgT and hTERT cells included CREB signaling in neurons (cellular plasticity), G-Protein receptor coupled signaling (signal transduction), phagosome formation (tissue remodeling and inflammation), and breast cancer regulation by Stathmin 1 (nucleus microtubule dynamics)." (PMID 37762531, 2023). "In breast cancer patients, high STMN1 correlates with poor prognosis." (PMID 36009568, 2022). "Similarly, the high expression of STMN1 was confirmed in other cancers, including colorectal cancer, liver cancer, gastric cancer, and breast cancer." (PMID 35186166, 2022). "Stathmin 1 is an oncoprotein that is associated with negative prognosis in patients with breast cancer." (PMID 33924764, 2021). "In particular, common genes resulted to be associated with the Cancer drug response by drug efflux and PXR/RXR activation pathways, as well as to Breast cancer regulation by Stathmin 1, 14-3-3-mediated signalling and NRF2-mediated oxidative stress response pathways." (PMID 31624308, 2019). "Some pathways specifically involved in breast cancer were found among canonical pathways predicted by the IPA at 24 h and 48 h, included Estrogen-Mediated S Phase Entry, Hereditary Breast Cancer Signaling, Breast Cancer Regulation by Stathmin 1, Estrogen Synthesis." (PMID 29202775, 2017). "Pathway analysis of the contents of the TIS EVs using Ingenuity pathway analysis (IPA) revealed the following pathways; remodelling of epithelial adherans junctions, EIF2 signalling, breast cancer regulation by stathmin 1, phagosome maturation and epithelial adherens junction signalling pathways." (PMID 28991260, 2017). "FOXM1 induces STMN1 expression in B-cell lymphoma, breast cancer and gastric cancer." (PMID 26973435, 2016). "Knockdown or low levels of stathmin 1 could sensitise breast cancer cells to paclitaxel, vinblastine or docetaxel respectively demonstrating its importance in determining the responsiveness of cancer cells to chemotherapeutics." (PMID 26878873, 2016). "Currently, Stathmin1 (STMN1) and phospho-STMN1 levels in breast cancers and their clinical implications are unknown." (PMID 26087399, 2015). "Therefore, STMN1 serves as a target for antimicrotubule therapies in ovarian cancer, consistent with the previous results shown in breast cancer." (PMID 25897432, 2015). "Moreover they also appeared in the canonical pathway analysis of ephrin A Signaling, RhoA signaling, PEDF signaling, breast cancer regulation by stathmin 1 and signaling by Rho family GTPases of antidepressant-treated women." (PMID 25628539, 2014). "Interestingly, our results showed that the expression of miR-101 was also inversely correlated with the Stmn1 mRNA level not only in breast cancer cells, but also in breast cancer tissues." (PMID 23071542, 2012). "Thus, an evident inverse relationship was showed between the expression of miR-101 and Stmn1 in human breast cancer." (PMID 23071542, 2012). "The expression pattern of Stmn1 was opposite with miR-101 in breast cancer tissues, indicating that miR-101 may be involved in regulating breast carcinogenesis by interacting with Stmn1 in vivo." (PMID 23071542, 2012). "In the present study, we defined the expression profile of miR-101 and its target gene, Stathmin1 (Stmn1), in breast cancer tissue and adjacent normal breast tissue, and studied the pathophysiological significance of miR-101 in breast cancer using in vitro cell model." (PMID 23071542, 2012). "In the future, other targets of miR-101 besides Stmn1 still need to be identified in breast cancer." (PMID 23071542, 2012). "Additionally, the mRNA level of Stmn1 was remarkably increased in 83.33% (25/30 samples) of breast cancer tissues." (PMID 23071542, 2012).
breast carcinoma (continued). "Stmn1 was overexpressed in breast cancer samples of 85.71% (6/7 samples) of triple negative, 87.50% (7/8 samples) of ER/PR+, HER2+, 77.78% (7/9 samples) ER/PR+, HER2− and 83.33% (5/6 samples) of ER/PR−, HER2+, when compared with that in adjacent normal breast tissues, respectively." (PMID 23071542, 2012). "Thus, we speculated that miR-101 may exert its tumor suppressor function at least in part by regulating the expression of Stmn1 during the occurrence of breast cancer." (PMID 23071542, 2012). "Forkhead box M1 (FoxM1) directly regulates STMN1 gene transcription to overexpress tSTMN1 and confer resistance to paclitaxel in SKBR3 breast cancer cells." (PMID 40723207, 2025). "Suppressed autophagy on the account of miR-101 is reported in breast cancer (targeting RAB5A, STMN1 and ATG4D), HCC (through EZH2) and in ischemic liver (via activating mTOR signaling pathway)." (PMID 32124227, 2020). "Over-expression of miR-101 has a tumor-suppressive effect in breast cancer, and miR-101 has been shown to negatively regulate oncogenes including EZH2 and STMN1." (PMID 24475105, 2014). "In contrast to the breast cancer cell lines, the NMuMG mammary gland cell line will undergo epithelial mesenchymal transition (EMT), and they express the MET receptor and low STMN1 levels required to undergo EMT." (PMID 40723207, 2025). "The interaction between STMN1 and GRP78 correlated with breast cancer cell migration ability." (PMID 35186166, 2022). "In breast cancer, miR-101 has been reported to act as a suppressor of cell proliferation by decreasing the level of DNA methyltransferase 3A (DNMT3A) and targeting proteasome maturation protein (POMP) and Stathmin 1 (Stmn1)." (PMID 34272359, 2021). "We hypothesized that the cellular phosphorylation levels of STMN1 at four serine residues, as determined by immunohistochemistry, are related to DFS in breast cancer." (PMID 26087399, 2015). "More importantly, Stmn1 was observed to overexpress in human breast cancer tissues, which was not restricted to a specific sub-group of breast carcinoma." (PMID 23071542, 2012).